IUR1 (imatinib upregulated ABL suppressing lncRNA 1)
Gene: Long non-coding RNA gene on chromosome 11 (73,157,173 to 73,182,971, reverse strand). Ensembl gene ENSG00000289625.
Diseases named in the same sentence as IUR1 in open-access papers:
IUR1 is named in the same sentence as 4 diseases in open-access papers, as found by Europe PMC text mining. Sharing a sentence is not in itself a finding about the gene and the disease. The quoted sentences say what the papers report.
tumor (1 paper, 2022). "Abl-transformed cell survival and xenografted tumor growth in mice were evaluated to dissect the role of imatinib-upregulated lncRNA 1 (IUR1) in Abl-induced tumorigenesis." (PMID 34980123, 2022). "In the present study, we identified an lncRNA IUR1 as a critical negative regulator of Abl-induced tumor formation." (PMID 34980123, 2022).
IUR1 also shares sentences with these, for which no sentence is quoted: acute lymphoblastic leukemia (1 paper); chronic myeloid leukemia (1); leukemia (1).